CXCL1 (C-X-C motif chemokine ligand 1)
Diseases named in the same sentence as CXCL1 in open-access papers (continued):
Sharing a sentence is not in itself a finding about the gene and the disease.
tumor (continued). "Consistently, blockade of CXCR2 systemically in mice instead of tumor cells only could reduce engraftment rates of tumor cells homing to liver after IR injury, indicating that CXCL1/CXCR2 signaling is critical in PARP-1-induced susceptibility of the liver to recurrence." (PMID 29179487, 2017). "Furthermore, we found the expressions of CXCL1 and its receptor CXCR2 were significantly increased 30 min after 8 Gy of radiation in KYSE-150 and KYSE-30, which may cause a constitutively activated CXCL1/CXCR2 signaling in tumor cells." (PMID 28518141, 2017). "As expected, macrophage engulfment of debris, tumor growth, NETosis, and CXCL1/2 and CFB expression were obviously reduced in the presence of UNC2250." (PMID 41480760, 2026). "IL‐8, IL‐6, and CXCL1 are factors involved in neutrophil recruitment, and neutrophils contribute to tumour progression." (PMID 41503680, 2026). "In contrast, CytoB reduced phagocytosis of macrophages cocultured with tumor debris and decreased the induction of CXCL1/2 and CFB expression in macrophages." (PMID 41480760, 2026). "It provides a comprehensive overview that allows for an in-depth understanding of the importance of CXCL1 in tumor-related processes." (PMID 41898553, 2026). "Of note, heat denaturation, rather than nuclease application, more significantly reduced the production of Cxcl1/2 and Cfb mRNA induced by tumor debris, indicating that proteins from tumor debris were more critically involved." (PMID 41480760, 2026). "CXCL1 has been confirmed to regulate the formation of the tumor microenvironment and the behavior of cancer cells." (PMID 41360767, 2025). "Tumor cell intrinsic SETD2-H3K36me3 loss increases PI3K–AKT signaling, leading to robust expression of CXCL1 and GM-CSF, that together recruit neutrophils and reprogram them to be immunosuppressive." (PMID 40663561, 2025). "Circulating neutrophils express the chemokine receptors CXCR1 and CXCR2, and their recruitment to tumour tissues is regulated by CXCL1 and CXCL2, which are the focus of several immune therapy strategies." (PMID 40434054, 2025). "High-risk genes (TNF, CXCL1, CCL20, ITGA5, CXCL3) typically promote tumor progression and immune evasion by inducing the expression of chemokines or modulating cellular responses to chemokines." (PMID 40517358, 2025). "What’s more, STAT3 upregulates chemokines like CXCL1 (C-X-C Motif Chemokine Ligand 1) and attracts MDSCs to tumor sites." (PMID 40881676, 2025). "Studies on human umbilical vein endothelial cells (HUVEC) have shown that ionizing radiation increases CXCL1 expression in these cells, which indicates that radiation therapy can induce tumor angiogenesis and thus tumor growth." (PMID 40427171, 2025). "Herein, our analysis identifies gene expression changes across H. pylori–associated disease progression, with hub genes like CXCL1 and TPX2 showing early bacterial effects and later tumor-driven changes." (PMID 40445003, 2025). "By secreting chemokines (e.g. CXCL-1) and interleukins (e.g. IL-6), CAFs contribute to an inhibitory immune microenvironment of the pancreas and promote pancreatic cancer tumor growth." (PMID 40259388, 2025). "CAFs can also exert indirect effects on cells within the tumor stroma through paracrine signaling as they secrete proteins such as chemokines (i.e. CXCL1), interleukins (e.g. IL-6) and growth factors (i.e. EGF) that influence immune response and proliferation." (PMID 40259388, 2025). "Attraction of mobilized neutrophils to the tumor site is realized via chemokines CXCL1, CXCL2, CXCL5, CXCL6, and CXCL8 (IL-8) through CXCR1/2 and CXCL12 (SDF-1) and its receptor CXCR4." (PMID 40050933, 2025). "For example, in colorectal cancer, the m6A methyltransferase METTL3 promotes transcription factor m6A-BHLHE41 to increase CXCL1 transcription, which when secreted, recruits immunosuppressive MDSCs to the tumor." (PMID 40663561, 2025).
tumor (continued). "MDSC accumulation occurs within the GBM microenvironment through the interaction of tumor-derived chemokines (CXCL1/2/3) with their receptor CXCR2." (PMID 40948940, 2025). "In a mouse triple-negative breast cancer (4T1) lung metastasis model, 5-FU elevated ROS in tumor cells, activating NF-κB signaling and upregulating CXCL1 and CXCL2 to recruit neutrophils." (PMID 40805288, 2025). "This receptor helps release myeloid cells from the bone marrow and guides them toward tumor areas with high CXCL1 levels." (PMID 40943634, 2025). "In the TME, various cellular constituents release CXCR2 ligands, such as CXCL1-8, creating a chemotactic gradient that guides neutrophils to the tumor." (PMID 40160822, 2025). "Other studies have confirmed the tumor‐derived secretion of CXCL1, which has multiple effects within the tumor microenvironment." (PMID 39764565, 2025). "Its presence in the hypoxic tumor microenvironment favors infection, intracellular persistence, epigenetic reprogramming of tumor cells, and induction of cytokines such as CXCL1, reinforcing more aggressive phenotypes." (PMID 40944094, 2025). "The induction of tumor cell migration by chemotherapy drugs is related in part to CXCL1 and other CXCR2 ligands." (PMID 40427171, 2025). "In GBM, tumor-derived CXCL1/2/3 and CXCR2 promote polymorphonuclear myeloid-derived suppressor cell (PMN-MDSC) mobilization and expansion." (PMID 40948940, 2025). "In this regard, CXCL1 is considered a pro-cancer chemokine that, among other functions, enriches the tumor microenvironment with neutrophils, macrophages, and neutrophil extracellular traps." (PMID 40388549, 2025). "Aging PSCs exhibit tumor-promoting functions: they promote cancer cell proliferation and migration through the CXCL1/CXCR2 axis." (PMID 40136652, 2025). "While the involvement of CXCL1 in tumor progression is well established, its relevance to cancer therapy remains underexplored." (PMID 40427171, 2025). "In glioma, tumor-associated microglia are converted to a phenotype with pro-tumorigenic features by the tumor microenvironment through chemokines such as CXCL1, and targeting these microglia can reduce tumor growth." (PMID 41322409, 2025). "Several tumor-derived chemokines, including CXCL1, which significantly promotes tumor angiogenesis, induce migration toward cancer foci by activating MC surface receptors." (PMID 40960294, 2025). "Sca-1high LMSCs can directly increase tumor cell migration through the secretion of chemokines such as CXCL1." (PMID 40634316, 2025). "CXCL1 plays a significant role in tumour progression and is responsible for angiogenesis by directly acting on endothelial cells in breast cancer." (PMID 40852716, 2025). "We further analyzed IL-8 infiltration in tumor tissues from different groups using WB and found that the depression model significantly increased CXCL1 expression levels (the homolog of IL-8 in mice) in tumor tissues." (PMID 40839237, 2025). "Firstly, the necrosome activation in pancreatic cancer cells led to the secretion of CXCL1, a chemokine that promotes tumor growth and metastasis." (PMID 40064873, 2025). "In contrast, CXCL1 has diverse roles in cancer, promoting tumor growth and metastasis while enhancing the anti-tumor immune response." (PMID 40108668, 2025). "Crucially, Neutrosome (L) adsorbs tumor-derived inflammatory cytokines (e.g., IL-8/CXCL1), disrupting chemotactic gradients and reducing neutrophil migration toward tumor sites by 68%." (PMID 40528159, 2025).
tumor (continued). "The results confirmed that the mRNA expression levels of Cxcl1 and Cxcl2 were decreased in Il7r-KO tumor cells, while the expression of Cxcl3 remained unchanged." (PMID 41360767, 2025). "Tumor cells and surrounding stromal cells secrete CXCL1, creating a chemotactic gradient that attracts monocytes from the circulation into the tumor tissue, where they further differentiate into TAMs." (PMID 40636690, 2025). "Studies using animal models of ETBF-associated carcinogenesis have revealed that BFT exacerbates tumor development by promoting the production of pro-inflammatory cytokines, including interleukin-17A (IL-17A) and CXCL1, in the MinApc+/− mouse model." (PMID 40650003, 2025). "In CRC and HCC, CXCL1 fosters a tumor-promoting inflammatory environment by supporting cancer cell survival and proliferation." (PMID 40127075, 2025). "CXCL1 is involved in recruiting granulocytic myeloid-derived suppressor cells (G-MDSC) and tumor-associated neutrophils (TAN)." (PMID 40427171, 2025). "CXCL1 enhanced the recruitment of myeloid-derived suppressor cells (MDSCs), a population of immune cells that play a suppressive role in anti-tumor immune responses, thereby creating an immunosuppressive microenvironment conducive to cancer progression." (PMID 40064873, 2025). "In OSCC, CXCL1 induces the transformation of normal oral fibroblasts (NOFs) into senescent CAFs via an autocrine mechanism, thereby promoting tumor growth." (PMID 41445742, 2025). "Platelets play a crucial role in tumor metastasis and immune suppression, as they secrete pro-inflammatory factors such as CXCL1 and CXCL4, facilitating leukocyte recruitment and promoting tumorigenesis and progression." (PMID 41561757, 2025). "High expression of the ligands of Cxcr2, such as Cxcl1, Cxcl2, Cxcl3, and Cxcl5, was observed mainly in tumor cells, fibroblasts, chondrocytes, pericytes and osteoclasts among APM‐naïve cells." (PMID 40433925, 2025). "The directional movement of PMN-MDSCs is modulated by the release of C-X-C motif chemokines from tumor cells, including CXCL1, CXCL5, CXCL6, CXCL8, and CXCL12." (PMID 40722739, 2025). "In parallel, ERO1α has also been shown to modulate the tumor immune microenvironment—specifically, it enhances the oxidative folding and secretion of immunosuppressive cytokines such as G-CSF, CXCL1, and CXCL2, which are instrumental in recruiting PMN-MDSCs." (PMID 41226317, 2025). "In PDAC, P. gingivalis, an important pathogenic bacterium in the oral cavity, can promote the secretion of chemokines (CXCL1 and CXCL2) in the tumor microenvironment (TME), thereby recruiting tumor-associated neutrophils (TANs) in the TME to release NETs." (PMID 40102723, 2025). "Such innate immune cells are recruited to chronically inflamed tissues and tumours by diverse chemoattractants, including CXCL1, CXCL2, CCL2, CCL3, CCL4 and more chemokines and cytokines." (PMID 40434054, 2025). "For this reason, high CXCL1 expression in the tumor is a factor that enhances resistance to anti-angiogenic therapies." (PMID 40427171, 2025). "This dual function is well documented in melanoma, which expresses chemokines such as CCL2, CCL5, CXCL1, CXCL2, CXCL3, and CXCL8 which have been implicated in tumor growth and progression." (PMID 40943634, 2025). "In liver cancer, nuclear PHGDH forms a complex with c-Myc, which drives chemokine CXCL1 and IL8 expression, required to recruit neutrophils and tumor associated macrophages to the liver, sustaining tumor progression." (PMID 40640948, 2025). "TAMs, a crucial element of the TNBC IME, have the ability to secrete numerous pro-tumorigenic factors, including CXCL8 and CXCL1, which influence tumor cell behavior and foster the development of tumor spheroids in TNBC cells." (PMID 40149989, 2025).
tumor (continued). "CD66b+ neutrophil-like monocytes accumulate in the tumor microenvironment, likely in response to tumor-derived signals, including cytokines and chemokines such as IL-8, GM-CSF, and CXCL1." (PMID 40731885, 2025). "CXCL1 has been shown to facilitate the recruitment of granulocyte MDSCs (G-MDSCs) to the tumor niche in embryonic stem cells (ESCs)." (PMID 40134607, 2025). "Mechanistically, tmTNF+ neutrophils engage TNFR2 on tumor cells, inducing reciprocal CXCL1/IL-6 upregulation (feedforward loop) and driving iCAF differentiation." (PMID 40948749, 2025). "Blocking GPR35 signaling also reduces the secretion of angiogenic factors, including vascular endothelial growth factor (VEGF) and CXCL1, thereby inhibiting tumor angiogenesis and tumor cell proliferation." (PMID 41459506, 2025). "In a mouse model, it was shown that application of the P300 inhibitor (C646) effectively inhibited tumor growth even when CXCL1 levels were increased." (PMID 40943634, 2025). "Previous studies have demonstrated that BFT-induced CXCL1 production facilitates myeloid cell infiltration into tumor sites, accelerating polyp formation, particularly in the distal colon." (PMID 40650003, 2025). "Compared to adjacent normal cells, tumor colonocytes overexpressed chemokines (CXCL1, CXCL2, CXCL3, and CCL20), showing significant effects on inflammatory processes and immune cell recruitment." (PMID 40240912, 2025). "Mechanistically, tumor-derived CXCL1 activates TAMs via paracrine secretion, driving their M2 polarization and stimulating EGF secretion." (PMID 41445742, 2025). "CXCL1 is a significant factor in cancer processes, inducing an autocrine stimulation of tumor cell proliferation and migration." (PMID 40427171, 2025). "In head and neck squamous cell carcinomas, inhibiting the triple combination of IL-6, IL-8, and CXCL-1 has been shown to be highly effective in reducing tumour cell activity." (PMID 41009413, 2025). "CXCL1 and its receptor CXCR2 are overexpressed and linked to tumor progression, highlighting their diagnostic and therapeutic potential." (PMID 40943634, 2025). "G31P inhibits AKT and ERK phosphorylation by directly blocking CXCR1/2 signaling in tumor cells and indirectly decreases CXCL1/8 driven paracrine activation, consistent with evidence that CXCR1/2 blockade inhibits PI3K/AKT signaling in multiple cancers." (PMID 41425704, 2025). "CXCL1 is part of the senescence-associated secretory phenotype (SASP), involves its role in the tumor microenvironment, and helps wake up dormant cancer cells, making them more aggressive and prone to recurrence." (PMID 40791849, 2025). "These EV-educated macrophages secreted factors like CXCL1 and TGFβ, which remodeled the tumor stroma and immune environment and enhanced tumor invasion." (PMID 40103824, 2025). "CXCL1, a chemokine well documented for its role in regulating tumor-infiltrating immune cells, was found to be upregulated after suppression of STK11." (PMID 41051525, 2025). "Tumor CXCL1 expression has been shown to drive cancer cell proliferation, migration, invasion and angiogenesis in a CXCR2-dependent manner." (PMID 40108668, 2025). "CXCL1 chemokine induces angiogenesis and recruitment of G-MDSCs and neutrophils into the tumor niche." (PMID 40427171, 2025). "Tumor-derived CXCL1 further activates STAT3/NF-κB pathway in adipocytes to promote IL6 expression and secretion in adipocytes, and finally forms a cascade of interaction." (PMID 40841364, 2025). "This pro-carcinogenic role of RIPK3 was attributed to a necroptosis-independent function that elicited macrophage-induced anti-tumor immune suppression through CXCL1/Mincled signaling." (PMID 39971907, 2025). "CXCL1 is an important chemokine in the development of many inflammatory diseases, promoting neovascularization, inflammatory response, and tumor formation." (PMID 40455858, 2025).
tumor (continued). "The interaction between CAFs and ESCC cells induces CXCL1 expression in autocrine/paracrine signaling loops, further enhancing tumor radioresistance." (PMID 40134607, 2025). "In our direct co-cultures, we observed an early increase in IFN-γ secretion and enhanced tumor cell killing activity, followed by a decrease in IL-1β, IL-4 and IL-6 levels alongside an increase in soluble CXCL1." (PMID 40108668, 2025). "CXCL1 present in extracellular vesicles derived from apoptotic cancer cells also contributes to tumor immune evasion." (PMID 40427171, 2025). "The overproduction of CXCL1 was notably related to larger tumor size, more advanced stage, deeper invasion, and spread to lymph nodes." (PMID 40943634, 2025). "CXCL1 is a chemokine extensively documented for its role in modulating tumor-infiltrating immune cells." (PMID 41051525, 2025). "This study further demonstrated that the expression of CXCL1 is regulated by IL-7R signaling: tumor cells with high IL-7R expression upregulate CXCL1 to drive the polarization of immunosuppressive macrophages." (PMID 41360767, 2025). "To confirm the inhibition of tumor growth associated with decreased chemokine expression in Ccn1‐KO tumor, we focused on CXC chemokines, including CXCL1, CXCL3, and CXCL5, which bind to CXCR2, as well as CCL2 and CCL7, which bind to CCR2." (PMID 40287974, 2025). "In the context of tumour progression, CXCL1 promotes tumour cell migration, thereby contributing to metastasis." (PMID 41165410, 2025). "Knockdown of MAGEA6 significantly reduced CRC cell migration, invasion, and PNI both in vitro and in vivo; 3) MAGEA6 promotes YY1 deubiquitination, enhancing CXCL1 expression and SC recruitment, while also driving tumor cell EMT." (PMID 40145793, 2025). "This means that an increase in CXCL1 expression can be a marker of TNFR2 expression on a tumor cell and decreased TNFR1 expression." (PMID 40427171, 2025). "These factors activate the CXCL1/CXCR2 feedback loop, leading to increased recruitment of tumor-associated neutrophils (TANs) and granulocytic myeloid-derived suppressor cells (G-MDSCs)." (PMID 39409924, 2024). "Neutrophils are recruited to the PDAC TME via multiple tumour-secreted chemokines including CXCL1, CXCL2, CXCL5, and CXCL8." (PMID 38384463, 2024). "It is now a consensus that tumor-associated neutrophils (TANs) or PMN-MDSCs have a significant impact on tumorigenesis and CXCL8 and CXCL1/2 are of the most outstanding chemokines promoting protumoral immune responses." (PMID 38786066, 2024). "In a mouse model, treatment with a CXCL1-neutralizing antibody blocked the chemotactic and NET-promoting properties of KDM6A-deficient PDAC cells and suppressed tumor growth, highlighting its potential as a targeted treatment strategy." (PMID 38791111, 2024). "Tumor cells, identified as CK positive cells, expressed high levels of CXCL1 and low levels of CXCL2." (PMID 39639338, 2024). "Specifically, CAR T-cells modified to express the chemokine receptor CXCR2, which interfaces with the ligand CXCL1 present on melanoma cells, exhibited proficient migration toward the tumor microenvironment." (PMID 38612592, 2024). "The GAC is a major component in the ECM and affects many properties of the tumor; one of the mechanisms can be the recruitment of the neutrophils via the CXCL1/CXCR2 interaction." (PMID 38474175, 2024). "More importantly, the tumor tissue immunofluorescence experiment clearly showed that Flag-tagged CXCL1 was predominantly phagocytosed by CD206+ TAMs in the TME, which promoted PD-L1 expression and subsequent M2 polarization." (PMID 38654356, 2024).